IL1R2 (interleukin 1 receptor type 2)
Diseases named in the same sentence as IL1R2 in open-access papers (continued):
Sharing a sentence is not in itself a finding about the gene and the disease.
mastitis (3 papers, 2020 to 2024). Inflammation of breast tissue during lactation or postpartum due to an obstructed duct or infection. "CmCGG DMEGs like IL6R, TNF, BTK, IL1R2, and TNFSF8 enriched in several immune-related GO terms and pathways indicated their important roles in host immune response and their potential as candidate genes for S. aureus mastitis." (PMID 33193625, 2020). "Moreover, genome-wide DNA methylation alteration in the format of CmCGG was significantly related to the immune response to S. aureus-induced mastitis, and several genes including IL-6R, TNF, BTK, IL-1R2, and TNFSF8 were identified as potential epigenetic markers of S. aureus mastitis." (PMID 33708235, 2020).
melanoma (3 papers, 2012 to 2022). A malignant, usually aggressive tumor composed of atypical, neoplastic melanocytes. "Interestingly, expression of genes of the pro-inflammatory network (e.g., IL-8, IL1R2) increased, whereas expression of members of the melanoma tumor specific antigen gene family decreased." (PMID 23109831, 2012). "From other validated targets in this study that have not yet been investigated in melanoma, we would like to point out MRAS, IL1R2, RAB34, LAPTM5, RDH10, and STK32C." (PMID 36139698, 2022).
non-small cell lung carcinoma (3 papers, 2022 to 2025). A group of at least three distinct histological types of lung cancer, including non-small cell squamous cell carcinoma, adenocarcinoma, and large cell carcinoma. "In addition IL-1R2 recently emerged as a tumor-infiltrating Treg associated marker in scRNA sequencing studies, in breast, colorectal or non-small-cell lung cancers, together with several immune-checkpoints." (PMID 35211118, 2022). "IL1R2 is also reported to be involved in the progression of osteosarcoma, non-small cell lung cancer, liver cancer, and lymphoma." (PMID 37728418, 2023). "Taking advantage of single cell-RNA (scRNA) sequencing, it has been shown that tumor-infiltrating Tregs express high levels of IL-1R2 compared to other lymphocytes, in particular in breast, colorectal or non-small-cell lung cancers." (PMID 35211118, 2022). "Our analysis was consistent with similar analysis completed in human non-small cell lung cancer in which PLAU, PLAUR, IL1R2, CD274, OSM, and CXCL8 were reported to be significantly enriched in TANs relative to circulating neutrophils." (PMID 39932553, 2025).
Stroke (3 papers, 2022 to 2025). Sudden impairment of blood flow to a part of the brain due to occlusion or rupture of an artery to the brain. "PPARα KO brains had upregulated expression of several genes already implicated in neural injury following stroke such as Mmp19, Il6, Saa3, and Il1r2." (PMID 40362325, 2025). "Although no studies have correlated the level of IL1R2 with stroke, a study on cardiomyocytes showed that IL-1R2 protected the heart from ischemia and reperfusion injury." (PMID 36118760, 2022).
acute kidney injury (2 papers, 2021 to 2025). Sudden and sustained deterioration of the kidney function characterized by decreased glomerular filtration rate, increased serum creatinine or oliguria. "Similar results were found among patients with Acute Kidney Injury (AKI) where the overexpression of genes such as MMP8, IL1R2, and OLFM4 was associated with increased severity and organ failure." (PMID 33692779, 2021). "Moreover, alterations in renal IL-1R2 expression were reported in association with multiple kidney pathology including chronic kidney disease (CKD), acute kidney injury (AKI), lupus nephritis, IgA nephropathy, RCC, and rhabdoid kidney tumor." (PMID 40486517, 2025).
anaphylaxis (2 papers, 2022 to 2023). An acute hypersensitivity reaction that occurs from exposure to an allergen. "Hub genes identified here (IL1R2, FOS, MMP9, DUSP1, and CLEC4D) represent a whole blood gene signature of anaphylaxis with STEMI predisposition and provide candidate diagnostic and therapeutic targets for follow-up studies." (PMID 37469874, 2023). "IL1R2, FOS, MMP9, DUSP1, and CLEC4D were screened and identified as hub genes shared by anaphylaxis and STEMI." (PMID 37469874, 2023). "Taking the intersection of six algorithms (DMNC, Stress, MCC, Degree, Closeness, Radiality) in cytoHubba, we found 6 hub genes shared by anaphylaxis and STEMI: IL1R2, S100A12, FOS, MMP9, DUSP1, and CLEC4D." (PMID 37469874, 2023). "In this study, we identified four approved drugs that have the potential to be repurposed against hub genes involved in anaphylaxis complicated STEMI, including anakinra, baclofen, andecaliximab, and albuterol targeting IL1R2, FOS, MMP9, and DUSP1, respectively." (PMID 37469874, 2023).
ankylosing spondylitis (2 papers, 2009 to 2023). An autoimmune chronic inflammatory disorder characterized by inflammation in the vertebral joints of the spine and sacroiliac joints. "IL1R2 has also been shown to be associated with ankylosing spondylitis." (PMID 37895311, 2023).
arteriosclerosis (2 papers, 2015 to 2020). A vascular disorder characterized by thickening and hardening of the walls of the arteries. "The expression of IL1R2 has been identified as a potential therapeutic target for several diseases including arteriosclerosis." (PMID 32727543, 2020). "In conclusion, our data show that although EC-derived IL-1α is key in driving graft arteriosclerosis, it is inactive in unstimulated ECs due to binding to IL-1R2." (PMID 26324711, 2015).
Atherosclerotic lesion (2 papers, 2022 to 2025). A lesion associated with atherosclerosis, a multifactorial and multipart progressive disease manifested by the focal development within the arterial wall of lesions, that ranges from the development of a fatty streak, plaque progression, and plaque disruption. "Interestingly, IL-1R2 has been found to be reduced in monocytes and macrophages in atherosclerotic lesions, whereas we find that the CD38+ TIM subclusters are enriched for IL-1R2." (PMID 40327401, 2025).
autoimmune disease (2 papers, 2019 to 2025). A disorder resulting from loss of function or tissue destruction of an organ or multiple organs, arising from humoral or cellular immune responses of the individual to their own tissue constituents. "In autoimmune diseases, IL-1R2 can control IL-1-driven inflammatory responses and serves as an important internal brake in the later stages of the immune response, limiting IL-1-dependent B cell activation and germinal center reactions, as well as antibody production." (PMID 40002719, 2025).
coronary atherosclerosis (2 papers, 2022 to 2025). Atherosclerosis of the coronary vasculature. "In patient with coronary atherosclerosis, the injury/inflammatory damage was prevented by IL1R2 which mediated by miR-383-3p to inhibit the inflammasome signaling pathway to active in endothelial cells of coronary artery." (PMID 40231027, 2025). "Recently, IL-1R2 has been identified as a pivotal mediator of a broad spectrumof inflammatory cytokines involved in the development of coronary atherosclerosis." (PMID 39076182, 2022).
depression (2 papers, 2022 to 2024). "Proteins associated with the anxiety/depression (IL-1R2 P = 0.11 and MATN2 P = 0.61) and cognitive groups (CTSO P = 0.64 and NFASC P = 0.41) were not different between men and women in either age group, consistent with the absent/weak association between sex and these outcomes identified by PLR." (PMID 38589621, 2024). "IL-1R2, MATN2 and COLEC12 were associated with cardiorespiratory symptoms, fatigue and anxiety/depression; MATN2, CSF3 and C1QA were elevated in gastrointestinal symptoms and C1QA was elevated in cognitive impairment." (PMID 38589621, 2024).
glioma (2 papers, 2020 to 2021). A benign or malignant brain and spinal cord tumor that arises from glial cells (astrocytes, oligodendrocytes, ependymal cells). "In addition, microarray analysis revealed that the PDGFB-driven glioma had a significant increase in other anti-inflammatory (M2) mediators, including IL1R2, IRF7, and STAT3." (PMID 33020472, 2020).
gram-positive bacterial infections (2 papers, 2021 to 2022). Infections caused by bacteria that retain the crystal violet stain (positive) when treated by the gram-staining method. "However, as few genes were highly up- or downregulated in the mallards treated with inactivated S. aureus more research is required to determine if IL1R2 is also a good marker for differentiating gram-negative and gram-positive bacterial infections in mallards." (PMID 34031452, 2021).
Hearing impairment (2 papers, 2009 to 2021). A decreased magnitude of the sensory perception of sound. "We hypothesize that AIED patients who experience a break in tolerance and fail to express IL1R2 in response to antigenic stimuli, have unopposed IL-1β expression that leads to hearing loss." (PMID 19401759, 2009). "SNP rs4141134 of IL1R2 had not been previously reported to be associated with hearing impairment." (PMID 34865658, 2021).
idiopathic pulmonary fibrosis (2 papers, 2021 to 2025). Idiopathic pulmonary fibrosis (IPF) is a nonneoplastic pulmonary disease that is characterized by the formation of scar tissue within the lungs in the absence of any known cause. "Furthermore, the authors found unusual levels of certain genes in the red module associated with idiopathic pulmonary fibrosis, specifically S100A12, S100A9, CLEC4E, CRIP1, and IL1R2." (PMID 40782499, 2025).
Insulin resistance (2 papers, 2019 to 2021). Increased resistance towards insulin, that is, diminished effectiveness of insulin in reducing blood glucose levels. "Interestingly, LUZP6 RNA is enriched in salivary exosomes and, together with another three genes (IL1R2, VPS4B and CAP1) comprising an RNA signature, could distinguish high from low insulin resistance as an extracellular RNA marker." (PMID 34073722, 2021).
ischemia (2 papers, 2022). A hypoperfusion of the BLOOD through an organ or tissue caused by a PATHOLOGIC CONSTRICTION or obstruction of its BLOOD VESSELS, or an absence of BLOOD CIRCULATION. "Besides, IL-1R2-overexpressed mice reduced the expressions of p-STAT1, IL-17RA, Bax, and in heart from mice with 45 min of ischemia followed by 3 h of reperfusion." (PMID 35087030, 2022).
ischemic stroke (2 papers, 2022 to 2024). A stroke disorder caused by obstruction of blood flow to the brain, due to thrombotic (local blood clot formation) or embolic (due to a blood clot or other material traveling from another site) event. "In studies of ICH and ischemic stroke (IS), Il1r2 has been implicated as an early response gene." (PMID 38271077, 2024). "In terms of its immunosuppressive role, laminarin stimulated interleukin 1 receptor type 2 (IL1R2) and inhibited human leukocyte antigen A (HLAA) in an ischemic stroke model." (PMID 36118760, 2022).
liver cancer (2 papers, 2023). An epithelial or non-epithelial malignant neoplasm that arises from the liver. "Thus, PAIP1 would positively regulated PTAFR and IL1R2 in both HepG2 cells and liver cancer tissues." (PMID 37101794, 2023). "Thus, more work could be conducted to explore the roles of PTAFR and IL1R2 in liver cancer." (PMID 37101794, 2023).
osteonecrosis (2 papers, 2019 to 2020). A none disease characterized by death of bone tissue due to a lack of blood supply. "Another study reported that the IL1R2 SNP rs11674595:T > C showed an increased risk of osteonecrosis of the femoral head (ONFH)." (PMID 32252823, 2020).
pancreatic cancer (2 papers, 2010 to 2025). "IL‐1R2, an IL‐1 decoy receptor, is overexpressed in various cancers (tissues and/or serum), including breast, gastric, and pancreatic cancers, and is linked to a poor prognosis." (PMID 40517318, 2025). "IL1, the ligand of IL1R2 is known to be secreted by pancreatic cancer cells." (PMID 20808857, 2010). "By means of quantitative RT-PCR we could for the first time validate an upregulation of IL1R2 in pancreatic cancer." (PMID 20808857, 2010).
peritonitis (2 papers, 2024 to 2025). Inflammation of the peritoneum (tissue that lines the abdominal wall and covers most of the organs in the abdomen). "In mouse models of peritonitis and neuro-inflammation, IL-1R2 deficiency led to increased monocyte infiltration and exacerbated disease severity." (PMID 41293423, 2025). "Using a sterile peritonitis model, we examined the effect of IL-1R2 loss without the high level of IL-1R2 in the circulation, which showed increased neutrophil recruitment in response to IL-1α in R2–/– mice." (PMID 38329807, 2024).
psoriasis (2 papers, 2018 to 2025). An autoimmune condition characterized by red, well-delineated plaques with silvery scales that are usually on the extensor surfaces and scalp. "The same ROC analysis was also performed in the psoriasis group, and the AUC of IL1R2, AQP9, ZNF14 and H2BC5 were obtained to be 78.728%, 78.698%, 92.194% and 80.562%." (PMID 40093802, 2025). "In the CD group, the AUC of diagnostic genes H2BC5 and AQP9 were 61.333% and 93.909%, in the psoriasis group, the AUC of IL1R2, AQP9, ZNF14 and H2BC5 were 75.641%, 82.906%, 93.162%, and 51.709%." (PMID 40093802, 2025).
vasculitis (2 papers, 2021 to 2024). "It is pointed out that IL1R2 is upregulated in vasculitis and AMI patients." (PMID 34336943, 2021).
viral infection (2 papers, 2023 to 2024). "Here, we found MO IL-1R2 in the vast majority of patients with microbiologically confirmed bacterial and viral infection, an unexpected result as most of the patients were not seriously ill." (PMID 39519183, 2024).
alcoholic cirrhosis (1 paper, 2023). "Therefore, our findings suggest that RNASE2 mono, IRF1 mono, IL1R2 mono, and H1-4 mono could be the origin of macrophages and may transform into two distinct types of monocytes and macrophages during the progression of alcoholic cirrhosis." (PMID 36845083, 2023).
Autoimmunity (1 paper, 2010). The occurrence of an immune reaction against the organism's own cells or tissues. "Therefore, the ability of Tregs to express and release IL-1R2, and possibly also IL-1RA, locally to neutralize IL-1β function could play an important role in dampening inflammation and autoimmunity." (PMID 20066156, 2010).
Behçet’s disease (1 paper, 2025). "Notably, high IL-1R2 expression has also been observed in Behçet’s disease (BD), another type of vasculitis that affects large vessels." (PMID 40721841, 2025).
cerebral malaria (1 paper, 2025). A sequestration of Plasmodium falciparum in the brain, which can cause coma and/or seizures. "MMP8, IL1R2, and ARG1 transcription is higher across cerebral malaria, severe malarial anemia, and concurrent cerebral malaria and severe malarial anemia, indicating a shared inflammatory signature." (PMID 40383794, 2025).
cervical tumor (1 paper, 2019). "Furthermore, dysregulation of IL1R2 has been detected in high‐grade squamous intraepithelial lesion (HSIL) and squamous cell carcinomas (SCC) in invasive cervical cancer, which ascertains its implication in cervical tumor progression." (PMID 30460760, 2019).
colorectal tumor (1 paper, 2021). "Regarding the expression of the IL1β receptors, IL1R1 and IL1R2, IL1R1 was strongly expressed in fibroblasts while colorectal tumor cell lines expressed extremely low levels of the receptor." (PMID 34066976, 2021).
encephalitis (1 paper, 2025). An acute inflammatory process affecting the brain parenchyma. "The resultsrevealed upregulation of the MET proto-oncogene receptor tyrosine kinase (MET)and KIT proto-oncogene receptor tyrosine kinase (KIT) in the encephalitis group,while interleukin 1 receptor type 2 (IL1R2) was downregulated compared to thenon-SAE group." (PMID 40985687, 2025). "The decreased expression of IL1R2 in the encephalitis group mayremove the negative regulation on the IL-1 signaling pathway and contribute toexcessive inflammation." (PMID 40985687, 2025). "Our results indicate that, comparedto the non-encephalitis group, the encephalitis group shows significant upregulationof immune-related genes MET and KIT, while IL1R2 is downregulated." (PMID 40985687, 2025). "Specifically, we identified six differentiallyexpressed immune genes—MET, KIT, IL1R2, MAFF, CD69, andCEBPD—between the encephalitis and non-encephalitis groups." (PMID 40985687, 2025).
endometrial cancer (1 paper, 2019). Primary or metastatic malignant neoplasm involving the endometrium (mucous membrane that lines the endometrial cavity). "In conclusion, the present study results indicated that rs4851527, rs3218896, and rs2072472 in the IL‐1R2 gene were associated with endometrial cancer susceptibility in the Chinese Han population." (PMID 30895748, 2019). "In this study, we investigate the influence of IL‐1R2 polymorphisms on endometrial cancer susceptibility in the Chinese Han population." (PMID 30895748, 2019). "First, our result is the first to find that the IL‐1R2 polymorphisms were associated with the risk of endometrial cancer in the Chinese Han population." (PMID 30895748, 2019). "Next, we further evaluated the association between the IL‐1R2 polymorphisms and endometrial cancer risk under the genetic models (codominant, dominant, recessive, and additive) by logistic regression analysis adjusting for age." (PMID 30895748, 2019). "More clinical and experimental data were needed to be collected to help us understand better the role of IL‐1R2 polymorphisms in the development of endometrial cancer." (PMID 30895748, 2019). "Given that age is a major endometrial cancer risk factor, we further evaluated the association between polymorphisms of IL‐1R2 and endometrial cancer risk by age stratified analysis." (PMID 30895748, 2019). "The purpose of this study is to investigate the influence of single nucleotide polymorphisms (SNPs) of IL‐1R2 on endometrial cancer susceptibility." (PMID 30895748, 2019). "Given the role of IL‐1R2 in immune regulation and inflammatory response, we hypothesized that common genetic polymorphisms in the IL‐1R2 gene may also influence the risk of endometrial cancer." (PMID 30895748, 2019). "To investigate this hypothesis, we recruited 293 patients with endometrial cancer and 579 healthy controls to investigate the association between polymorphisms in the IL‐1R2 gene and endometrial cancer risk in the Chinese Han women population." (PMID 30895748, 2019). "Therefore, additional studies are needed to confirm the association between IL‐1R2 polymorphisms and endometrial cancer risk with large samples." (PMID 30895748, 2019). "However, the influence of IL‐1R2 polymorphisms on endometrial cancer susceptibility in the Chinese Han population has not been reported yet." (PMID 30895748, 2019).
Hepatic fibrosis (1 paper, 2013). The presence of excessive fibrous connective tissue in the liver. "Various members of the hepatic fibrosis pathway were also differentially expressed (A2M and Col3A1 upregulated in females, and IL1R2 and EGF in males)." (PMID 23531366, 2013).
Hyperglycemia (1 paper, 2014). An increased concentration of glucose in the blood. "While mifepristone prevented fasting-dependent hyperglycemia (data not shown), it did not reduce gene expression of IL-1R2 or IL-1RA." (PMID 25071776, 2014).
infertile (1 paper, 2009). "Consequently, we investigated the presence of mRNA encoding IL-1 in the endometrium of animals with disparate disease outcomes and found that during Period 1, infertile animals had higher levels of IL1A and IL1B, and their cognate IL1R2, compared with fertile animals." (PMID 19476661, 2009).
inflammatory bowel disease (1 paper, 2024). A spectrum of small and large bowel inflammatory diseases of unknown etiology. "In addition, IL-1R2 has a strong genetic association to inflammatory bowel disease (IBD) in multiple reports." (PMID 38329807, 2024). "Individuals with inflammatory bowel disease have lower serum IL-1R2." (PMID 38329807, 2024).